IL22 (interleukin 22)
Diseases named in the same sentence as IL22 in open-access papers (continued):
Sharing a sentence is not in itself a finding about the gene and the disease.
fungal infections (38 papers, 2009 to 2025). "Furthermore, T-lymphocytes and Th17-associated cytokines (defective IL-17A, IL-17F, and IL-22 responses to Candida albicans antigens) responsible for the defense against fungal infection emerged from an early age." (PMID 38673639, 2024). "However, IL-17A has been described as the “signature cytokine” for Th17-cells and is – together with IL-22 – implicated in mucosal immunity against bacterial and fungal infections." (PMID 22216247, 2011). "Blocking the action of IL-22 could increase host susceptibility to bacterial and fungal infection." (PMID 27303405, 2016). "In fact, a surge in the production of antimicrobial peptides and mucins driven by IL-22 not only promotes defense against fungal infection but also shapes the microbiota composition." (PMID 38298919, 2023). "Further, a significant variation in IL-17A, TNF-β, IL-1β, IL-2, IL-4, IL-6, IL-8, IL-10, IL-22, and IL-12p70, between the uninfected group and the pulmonary bacterial and fungal infection group (P < 0.05) was observed." (PMID 36319826, 2022). "There were significant differences in IL-4, IL-6, IL-8, IL-10, IL-12p70, IL-1β, IL-2, TNF-β, IL-17, and IL-22 between the uninfected group and the pulmonary bacterial and fungal infection group (P < 0.05)." (PMID 36319826, 2022). "There is particular interest in IL-22, as it has been widely demonstrated to control fungal infection in the gut and in vaginal tissue." (PMID 33921294, 2021). "Interleukin-22 is integral to the repair of the injured lung and helps clear viral, bacterial, and fungal infection from the lung." (PMID 34597299, 2021). "Thus, the microbe driven IL-22 production can untwine how antibiotic-related dysbiosis and cancer therapy may predispose to secondary fungal infections and suggests that therapies aimed at restoring the AhR/IL-22 axis at the mucosal surface could be of therapeutic benefit." (PMID 32635461, 2020). "These mutations led to defective Th1 and Th17 lymphocyte responses and reduced IL-17, IL-22, and IFN-γ production, explaining the increased susceptibility to fungal infection." (PMID 32352976, 2020). "Chronic mucocutaneous candidiasis (CMC) is a monogenetic immunodeficiency of cell-mediated immunity that develops as a consequence of defects in IL-17 and IL-22 immunity required for defence against fungal infections." (PMID 32352976, 2020). "The finding that IL-33R/ST2 signaling suppresses IL-22 is novel, but a recent study revealed IL-33 regulates IL-17A and IL-22 in fungal infection." (PMID 31057534, 2019). "IL-22 plays an important role in fungal infections due to its ability of epithelial tissue repair and the induction of antimicrobial peptides." (PMID 28791025, 2017). "Interleukin-22 also contributes to protective immunity in the early stages of fungal infection with Candida albicans, Aspergillus fumigatus, and Rhizomucor pusilluscan." (PMID 27303405, 2016). "In fact, IL-22 at mucosal surfaces provides innate immune protection against bacterial and fungal infections and promotes inflammation and epithelial proliferation and repair." (PMID 27188997, 2016). "In a previous study we have identified that IFNγ treatment had beneficial effects on the immune status including IL-17 and IL-22 responses in a case series of patients with invasive fungal infections." (PMID 25888308, 2015). "Both IL-17 and IL-22 are cytokines that are thought to be protective in the host defence against invasive fungal infections." (PMID 24669841, 2014). "In conclusion, our data clearly show the essential role of IL-22 during early host defense against fungal infections with the two common Rhizomucor species." (PMID 23798999, 2013). "These defects are linked to the role that these proteins play in the activation of the multifaceted Th17 lymphocytes and their production of interleukins (e.g., IL-17 and IL-22) for epithelial host defense against fungal infection." (PMID 21197459, 2011).
fungal infections (continued). "Th17-type T cells, which produce IL-17, IL-17F, and IL-22, are thought to be important for inflammatory responses and the control of bacterial and fungal infections at mucosal surfaces." (PMID 19360100, 2009). "Additionally, IL-17 synergistically collaborates with IL-22 for a robust immune response against fungal infection, and their inhibition can lead to a compromised ability to control fungal infections." (PMID 39949778, 2025). "Brodalumab’s effect on IL-22 activity could theoretically weaken mucosal immunity, resulting in fungal infections like Candida albicans." (PMID 39911581, 2024). "Similarly, IL-17A functions as a key proinflammatory cytokine essential for defensing against bacterial and fungal infections, while IL-22 plays diverse roles in inflammation, mucous production, pathogen defense, wound healing, and tissue regeneration." (PMID 39328419, 2024). "Zebrafish have homologs for both il22 and il17a, and il22 mRNA expression is induced upon fungal infection in adult zebrafish, but their roles in fungal infections in larval zebrafish are unknown." (PMID 35333905, 2022). "The indole derivatives-induced AHR activation promotes the local synthesis of the anti-inflammatory cytokine IL-22 by the innate lymphoid cells; IL-22 protects the mucosa integrity against fungal infection by Candida albicans, commonly observed in patients with IBD." (PMID 35391730, 2022). "The clinical picture of CMC in our patients could be explained by diminished production of interleukin (IL)-17 and IL-22, cytokines important in the protection against fungal infections." (PMID 28348565, 2017). "We also observed a depletion of Th22 cells in FIII, a subset of mucosal CD4+T cells that provides innate immune protection against bacterial and fungal infections and promote inflammation and epithelial proliferation and repair by secretion of IL-22 and Th17 cells co-expressing IL-22." (PMID 25503054, 2014). "Similarly, in humans, IL-22 was demonstrated to be up-regulated during defense responses against fungal infections." (PMID 23798999, 2013). "IL-22 has been shown to mediate immunopathology in inflammatory diseases and to promote innate immune responses during intra- and extracellular bacterial or fungal infections." (PMID 23460846, 2013). "In addition, IL-22, deficiency affects the production of IL-17 by ILC3, which may contribute to increased Candida albicans fungal infections in experimental mouse models." (PMID 40568578, 2025). "Thus, oral immunity (innate or adaptive) modulation (regulation of Th17 cells, maintenance of the Treg balance, IL-22 induction, IgA production) may be greatly important to prevent or to treat fungal infections post-RT." (PMID 33921294, 2021). "Thus, IL-22 is likely to play a role in wound healing processes and/or immunity-related mechanisms, making it an intriguing candidate for the immunopathobiology of fungal infections, such as mucormycosis." (PMID 23798999, 2013). "Patients failed to increase IL-17A, IL-22, and IL-23, which are found critical for optimal host defense against cutaneous candidiasis and fungal infections." (PMID 28919897, 2017). "Antibodies specific for IFN-α7 and IL-22 were significantly more prevalent in patients with only bacterial infections and patients with mixed bacterial/fungal infections, and antibodies against IFN-α10, IL-17A, and TNF-α were more common in patients with mixed bacterial/fungal infections." (PMID 36752204, 2023).
lung carcinoma (36 papers, 2011 to 2025). "A more worrying finding comes from an in vitro study, where IL22 production was elevated in a cancer associated fibroblast culture and treatment of lung cancer cells with the supernatant of this culture resulted in enhanced proliferation and migration." (PMID 35433484, 2022). "In mice lung cancer models, the presence of the Kras mutation led to the activation of the NF-κB pathway and to the secretion of IL-6 and IL-17, which was related to the increase in the IL-22 secretion." (PMID 37894302, 2023). "In lung cancer (LC), studies have revealed increased IL-22 levels in patient sera and infiltration of IL-22-positive cells into primary tumors." (PMID 40806452, 2025). "Studies revealed that the overexpression of IL-22 induced lung cancer cell resistance against apoptosis via the activation of STAT3 and the inactivation of ERK 1⁄2." (PMID 36776832, 2023). "High IL-22 levels were detected in lung cancer patients, both in the primary lung tumors (bronchoalveolar lavage and bronchial washings) and in the circulating blood (in serum)." (PMID 37894302, 2023). "Previous studies have revealed that Th22 cells and IL-22 are correlated with various tumors, including gastrointestinal cancer, hepatocellular carcinoma, and lung cancer." (PMID 35669104, 2022). "Another study revealed that the expression of IL-22 and its receptor in tumor tissues was higher, when compared to that in adjacent tissues, in lung cancer patients undergoing surgery." (PMID 35669104, 2022). "It was observed that patients with lung cancer had a higher percentage of CD4+IL-22+IL-17− cells, when compared to healthy controls (controls vs. lung cancer patients: 1.93 ± 0.25% vs. 6.06 ± 0.65%, P < 0.0001)." (PMID 35669104, 2022). "It was found that there was a significant increase in tumor volume in IL-22-treated mice, when compared to control mice, at day 14, indicating that this can accelerate tumor growth in lung cancer-bearing mice." (PMID 35669104, 2022). "For instance, interleukin-22 (IL-22) was profoundly elevated in cell cultures of primary CAFs, and CAFs-secreted IL-22 aggravates the proliferation and metastasis of lung cancer cells via the PI3K-Akt-mTOR signaling pathway." (PMID 33819917, 2021). "IL-22 and Th22 cells are elevated in sera and tumor samples from patients with lung cancer and high IL22R1 expression is an indicator of poor prognosis in non-small cell lung cancer." (PMID 33692792, 2021). "The role of IL-22 in cancer progression has been recognized in some epithelial cancers, such as breast and lung cancer." (PMID 33390778, 2021). "Multi-platform profiling revealed that resistant lung tumors have increased infiltration of Th17 cells, which secrete IL-17 and IL-22 cytokines to promote lung cancer cell invasiveness and MEK inhibitor resistance." (PMID 33972557, 2021). "IL22 also plays an essential role in KRAS-mutant lung cancer by inducing an inflammatory tumor microenvironment and protects lung cancer cell stemness." (PMID 34944848, 2021). "It has also been reported that IL-22 elevated in lung cancer and renders lung cancer cells resistant to chemotherapy." (PMID 33042126, 2020). "Recently study has revealed high expression levels of IL22 in both lung tumors and serum of patients with lung cancer, promoteing Kras mutant lung tumorigenesis." (PMID 32201538, 2020). "In agreement to this, when IL-22 expressing TILs derived from HCC patients were introduced into lung cancer xenograft murine model, it orchestrated oncogenic signaling pathways in the tissue." (PMID 33042126, 2020). "Recent studies have shown that IL-22 enhances proliferation and migration of lung cancer cells via the IL-22R1/AKT and IL-22R1/STAT3 signaling pathways." (PMID 31750252, 2019). "IL-22 is overexpressed in lung cancer tissues, malignant pleural effusions, and NSCLC patient serum." (PMID 31750252, 2019).
lung carcinoma (continued). "To detect the expression of IL-22 in lung cancer tissues, we used qRT-PCR to analyze IL-22 mRNA in 20 EGFR-mutant NSCLC patients." (PMID 31750252, 2019). "An examination of the role of IL-22 in lung adenocarcinoma has shown that IL-22 in K-ras-driven lung cancer mediates tumor proliferation and remodeling of the tumor microenvironment in a mouse model." (PMID 31637216, 2019). "In patients with lung cancer, we were unable to find a relationship between IL-22 levels, systemic leukocyte, lymphocyte or neutrophil counts and CRP (p = 0.19, 0.33, 0.28 and 0.35, respectively)." (PMID 27388918, 2016). "Recently, we and others have found evidence for IL-22 as a mediator in the interaction between lung cancer cells and the immune environment." (PMID 27388918, 2016). "Analysis of a large cohort of patients suffering from lung cancer has revealed that IL-22 is frequently expressed in lung cancer tissue, but the clinical significance of these findings has yet to be addressed." (PMID 27388918, 2016). "In the present study, we analysed lavage specimens from 195 consecutive patients (37 with lung cancer) undergoing clinically indicated bronchoscopy and correlated IL-22 expression with local and systemic cell counts and with serum markers of inflammation." (PMID 27388918, 2016). "It has been reported that IL-22 overexpression in lung cancer cells protects the cells from apoptosis by activating STAT3, Bcl-2, and Ccl-xL and inactivating ERK1/2." (PMID 27445423, 2016). "Recently, this autocrine mechanism was demonstrated in human lung cancer cells secreting IL-22- and IL-6- induced STAT3 phosphorylation, thus contributing to the pathogenesis of lung adenocarcinoma and formation of pleural effusion." (PMID 25793261, 2015). "The protective effect of IL-22 is consistent with a previous report that IL-22 contributes to the chemotherapeutic resistance of human lung cancer cells through the activation of STAT3." (PMID 23519428, 2013). "IL-22 also protected lung cancer cell lines from serum-starvation-induced and chemotherapeutic drug-induced apoptosis by activation of STAT3 and its downstream antiapoptotic proteins and inhibition extracellular signal-regulated kinase 1/2." (PMID 21625390, 2011). "In non-small cell lung carcinoma (NSCLC), overexpression of IL-22 protected lung cancer cell lines from apoptosis, while downregulation of IL-22 significantly inhibited the human tumor cell growth in BALB/c nude mice." (PMID 21897855, 2011). "In addition to IL-17, Th17 cells produce other proinflammatory cytokines such as IL-21, IL-22, and IL-26, which are also related with lung cancer." (PMID 36776832, 2023). "In addition, it has been reported that IL-22 promotes proliferation of both human breast and lung cancer cells through the activation of the PI3K-AKT-mTOR pathway." (PMID 35336821, 2022). "This confirms that IL-22 simultaneously activates the JAK-STAT3/MAPKs/AKT pathway in lung cancer." (PMID 35669104, 2022). "Also, presumably NCR-ILC3s are pro-tumoral by secreting IL-17 in hepatocarcinoma and lung cancer whereas the IL-22 produced by these NCR-ILC3s promotes tumor growth and metastasis in breast and pancreas." (PMID 36341381, 2022). "After transfecting the human IL-22 cDNA into lung cancer A549 and PG cells, the overexpression of IL-22 inhibited the chemotherapy-mediated apoptosis of A549 and PG cells through the activation of STAT3 and its downstream antiapoptotic proteins, such as Bcl-2 and Bcl-xl." (PMID 35669104, 2022). "Besides growth factors, lung cancer cells produce different inflammatory modulators such as the interleukin family (IL‐6, IL‐8, IL‐17, IL‐22), tumor necrosis factor‐α (TNF‐α) and VEGF to promote their progression, invasion and angiogenesis." (PMID 35603909, 2022). "Next, we tested whether IL-17 and IL-22 cytokines secreted by Th17 cells promoted lung cancer cell drug resistance and invasion." (PMID 33972557, 2021).
lung carcinoma (continued). "In addition, AZD6244 treatment of human lung cancer cells showed a consistent upregulation of Th17-associated genes (TGF-β, IL6, IL23, IL17, IL22, IL1b, and RORγt)." (PMID 33972557, 2021). "The authors propose that pharmacologic targeting of IL-22 may have potential as an add-on therapy to conventional treatments of KRAS-mutant lung cancer." (PMID 33692792, 2021). "Similarly, inactivation of IL‐22 gene significantly reduced tumor number and size in lung cancer accompanied by reduced tumor cell proliferation." (PMID 31725949, 2020). "We speculate that although IL-22 is also produced by lung cancer cells, the expression level may be very low." (PMID 31750252, 2019). "IL-22 enhances tumor growth and induces chemotherapy resistance in human lung cancer cells." (PMID 31750252, 2019). "Low levels of IL-22 may be of prognostic relevance, as IL-22 is thought to promote a more aggressive lung cancer phenotype." (PMID 27388918, 2016). "Our results suggest that IL-22 in pulmonary lavage may serve as a marker for lung cancer, and, perhaps, for pulmonary metastases of other tumours." (PMID 27388918, 2016). "In vitro IL-22 promotes tumour growth and chemotherapy resistance of lung cancer cells." (PMID 27388918, 2016). "To investigate whether IL-22 is a marker of lung disease and especially of lung cancer or rather a reflection of systemic inflammation, we next analysed the relationship between IL-22 and systemic parameters of inflammation." (PMID 27388918, 2016). "Lavage IL-22 concentrations are highest in patients with pneumonia and lung cancer." (PMID 27388918, 2016). "As IL-22 is known to be elevated by acute or chronic inflammation, as seen in pneumonia, we excluded patients with known inflammatory lung diseases from the group of lung cancer patients for further analysis." (PMID 27388918, 2016). "In contrast, in lung cancer, the source of IL-22 remains uncertain." (PMID 27388918, 2016). "Indeed, IL-22 was described as an autocrine factor of human lung cancer cells contributing to cancer cell survival and resistance to chemotherapy, and its therapeutic effect was showed in an in vivo xenograft model using IL-22-RNAi plasmids." (PMID 25793261, 2015). "What precise roles do TGF-β, IL-6, IL-17, and IL-22 play in lung cancer immunopathology?" (PMID 24872958, 2014). "Also, IL-22 is elevated in lavage from patients with lung cancer." (PMID 31750252, 2019). "However, controversy remains as to the expression and function of IL-22 in lung cancer." (PMID 30473538, 2018). "Lavage IL-22 concentrations are high in patients with lung cancer but do not correlate with systemic inflammation, thus suggesting that lavage IL-22 may be related to the underlying malignancy." (PMID 27388918, 2016). "It thus strengthens the hypothesis that IL-22 has a role in lung cancer." (PMID 27388918, 2016). "IL‐22 stimulates STAT‐3‐mediated cell proliferation and stemness in cancer cells in colon, liver, gastric, pancreatic, and lung cancers." (PMID 31725949, 2020). "The PI3Kγ inhibitor AS-605240, another top candidate, was found to suppress lung carcinoma inflammation and the secretion of pro-inflammatory cytokines (e.g. IL-17, IFN-γ, IL-22, GM-CSF, IL-6, IL-4, and IL-13)." (PMID 33381110, 2020). "We focused on the function of IL-22 in EGFR-TKI resistance and found that IL-22 expression was higher in lung cancer tissues and plasma of patients with EGFR-TKI acquired resistance." (PMID 31750252, 2019). "A noteworthy finding of the present study is the dissociation between local IL-22 concentrations and systemic parameters of inflammation such as CRP and leukocyte counts in patients with lung cancer." (PMID 27388918, 2016). "Some of these cytokines (IL-6, IL-8, IL-10, IL-22, VEGF, TGF-β, and TNF-α) have also been studied to determine their role in lung cancer and are described in comparison to other cytokines next." (PMID 27445423, 2016).